BRAF (B-Raf proto-oncogene, serine/threonine kinase)
Diseases named in the same sentence as BRAF in open-access papers (continued):
Sharing a sentence is not in itself a finding about the gene and the disease.
melanoma (continued). "We applied Long's BRAF melanoma prognostic approach to our cohort based on our findings that LDH and number of metastases were both highly associated with survival." (PMID 35924450, 2022). "In order to study the effect of the selective regulation of the two STAT1 protein isoforms on PD-L1 expression, we depleted each of them separately by using specific siRNAs in the BRAF V600E mutant A375 melanoma cell line." (PMID 35267483, 2022). "Melanoma patients routinely receive either a combination of BRAF/MEK inhibitors or immunotherapy with antiPD1/DPL1 alone or in combination with antiCTLA4; the best sequence is still under discussion." (PMID 35159047, 2022). "A study analysing 132 melanoma samples that progressed with BRAF inhibitor treatment reported that a defined resistance mechanism was only identified in 58% of samples." (PMID 36292642, 2022). "Overall these data support the involvement of SEMA6A in the biology of BRAF-mut melanoma and indicate that SEMA6A is a prognostic indicator in this subset of patients." (PMID 35440004, 2022). "To address this unmet need, we synthesized a novel triphenylmethane, indolium 1, which has potent in vivo activity against LM36R (the counterpart of vemurafenib-sensitive LM36), which is an aggressive BRAF mutant melanoma that is vemurafenib-resistant." (PMID 35624662, 2022). "At the initiation of anti‐PD‐1 immunotherapy the median age was 64 years old, 101 (58%) individuals were male, and 48 patients (27.6%) had BRAF mutant melanoma." (PMID 35924450, 2022). "These BRAF inhibitor-resistant melanomas are also characterized by increased progression and metastasis." (PMID 36551563, 2022). "High MYC expression in BRAF‐mutant melanomas that progressed after BRAF inhibitor therapy was identified as the common denominator between diverse resistance pathways (ERK, PI3K, etc.)." (PMID 36214609, 2022). "Several miRNAs including miR-146a, miR-204-5p, miR-211-5p, miR-550a-3-6p, miR-199b-5p, miR-126-3p, and miR-204-5p have been proven to contribute to melanoma resistance to BRAF inhibitors or/and MARK inhibitors." (PMID 36499102, 2022). "Therapies targeting BRAF-mutated tumors, such as vemurafenib (PLX), have significantly improved the overall survival of melanoma patients." (PMID 36555289, 2022). "Mutations in the proto-oncogene BRAF and RAS family genes (KRAS and NRAS) are quite frequent in melanoma, CRC, anaplastic thyroid cancer (ATC) and LAC, whilst alterations affecting genes encoding MEK and ERK have rarely been identified." (PMID 35814399, 2022). "A similar role in protection against lipid peroxidation in BRAF-inhibitor resistant melanoma was shown for SREBP1, another master regulator of lipogenesis." (PMID 35255427, 2022). "Acquired oncogenic BRAF mutations result in the constitutive activation of BRAF→MEK→ERK (MAPK) pathway, which is necessary for melanoma growth and progression." (PMID 35785205, 2022). "The VE-BASKET (NCT01524978), a phase II trial, was a non-randomized, open-label, histology-agnostic basket study for patients with multiple BRAF V600E-mutant non-melanoma solid tumors." (PMID 36358795, 2022). "Patients with these melanomas respond well to combined BRAF/MEK inhibitors, but at least half the patients develop resistance within a year." (PMID 35323214, 2022). "Levels of miR-31-5p were inversely associated with expression of its target MEL gene EDNRB, known to play an essential role in normal melanocyte development as well as melanoma proliferation, metastatic initiation, and BRAF inhibitor resistance." (PMID 35810190, 2022). "Predictive or prognostic biomarkers to help selecting between both treatment options in BRAF mutant melanoma are largely missing." (PMID 35336796, 2022). "Recently, we have introduced a novel mathematical formalism allowing the representation of the relation between tumor heterogeneity and drug resistance and proposed several models for the development of resistance of melanoma treated with BRAF/MEK inhibitors." (PMID 35494017, 2022).
melanoma (continued). "Vemurafenib resistance is currently a persistent clinical problem in the management of BRAF mutant melanoma." (PMID 36210843, 2022). "NOTCH1 is downregulated in melanoma cell lines with intrinsic and acquired resistance to BRAF inhibition." (PMID 36202798, 2022). "Here, we compared the Idylla BRAF Mutation Test and the anti-BRAF V600E (clone VE1) immunohistochemistry (IHC) in 90 melanoma samples, with a focus on a challenging cohort of 32 positive sentinel lymph nodes." (PMID 35328303, 2022). "These recorded IC50 values were between 12.35 μg/mL (toward CCRF-CEM leukemia cells) and 26.66 μg/mL (toward SKMel-505 BRAF wild-type melanoma cells)." (PMID 35392644, 2022). "We also confirmed that the LATS1-SMAC endogenous interaction is regulated in a RASSF1A-dependent manner in another BRAF-driven melanoma cells SK-Mel239 and in the NRAS-driven melanoma cells SK-Mel2." (PMID 35941108, 2022). "For example, epidermal growth factor receptor (EGFR) mutations and ALK rearrangements are usually indicative of a lung cancer origin (most CUP cases), while BRAF and NRAS mutations are associated with melanoma." (PMID 35225863, 2022). "Different adaptive mechanisms have been reported to reduce the efficacy of mutant BRAF inhibition in melanoma." (PMID 35232962, 2022). "Paradoxically, the absence of endogenous MITF expression has also been be associated with MAPK inhibitor resistance, suggesting that either the excess or absence of MITF is permissive for cell viability under decreased MAPK signaling in BRAF-mutant melanoma." (PMID 35580987, 2022). "As a result three different BRAF inhibitors (BRAFi) have now been approved for BRAFV600E/K- mutant melanoma and have transformed the treatment of this disease." (PMID 35903549, 2022). "A recent report has suggested that targeting mTOR signaling overcame acquired resistance in BRAF-mutant melanoma, implying targeting signaling pathways bypass MAPK/MEK signaling to bring out great improvement." (PMID 36034784, 2022). "Melanoma cells with a loss of PTEN increased FN expression, thereby modifying signaling and attenuating the response to BRAF inhibitors." (PMID 35558554, 2022). "For patients with a malignant melanoma, molecular analysis was requested for the BRAF-gen in 13 cases and conclusive in 11 (85%)." (PMID 36605448, 2022). "In particular, BRAF-mutant melanoma cell lines expressing NGFRLow/AXLHigh are sensitive to SP2509, a Kdm1a inhibitor, only if not pretreated with MAPKi, probably by using the MAPK pathway to restore cell senescence." (PMID 36551603, 2022). "Some of the patients were recruited from a previously published retrospective analysis of advanced melanoma patients treated with BRAF ± MEKi and/or CPI between 2011 to 2021." (PMID 35565212, 2022). "Mutant KRAS appears to be involved in over 90% of PDAC, about 50% of CRC, about 30% of NSCLC and to a lesser extent in other tumors, while mutant BRAF has primarily been observed in melanomas." (PMID 35965494, 2022). "Genetic and pharmacological inhibition of ERK5 in melanoma cells leads to irreversible cellular senescence mediated by p21 and suppresses resistance to BRAF and MEK1/2 inhibition in vitro." (PMID 35806358, 2022). "Subsequently, BRAF inhibition results in paracrine suppressive activity of melanoma cells on dendritic cells by inhibiting their excretion of pro-inflammatory cytokines, namely IL-12 and tumor necrosis factor alpha (TNFα)." (PMID 35565255, 2022). "Much evidence has been provided that pro-survival autophagy is promoted by oncogenic BRAF, thus favoring melanoma cell survival and propagation." (PMID 36009541, 2022).
melanoma (continued). "Further studies with encorafenib have shown that used in combination with the MEK inhibitor binimetinib in metastatic BRAF-mutant melanoma cases, improves clinical response in terms of OS." (PMID 36358912, 2022). "We have previously shown preferential expression of SEMA6A in BRAF-mut cell lines and melanoma lymph-node metastases compared with BRAF-wt ones." (PMID 35440004, 2022). "Only seven (5.88%) patients with BRAF-positive melanoma received nivolumab or pembrolizumab PD-1 ICI as first-line treatment." (PMID 35885042, 2022). "Treatment of BRAF-V600E-expressing melanomas with combined BRAF/MEK inhibitor therapy (dabrafenib plus trametinib) has resulted in a 5-year survival rate of 34% in BRAF mutant metastatic melanoma." (PMID 35625881, 2022). "Targeted therapy with combination BRAF and MEK inhibitors is a key line of treatment in patients with advanced BRAF V600 mutant melanoma." (PMID 35133615, 2022). "We found PRRT3-AS1 was significantly highly expressed in melanoma, BRAF, NF1, RAS mutants, and Triple WT tissues, whereas DANCR showed limited expression difference." (PMID 36211371, 2022). "A recent study on acral nevi identified BRAF V600E mutation in 86% of samples, which is similar to what was observed in cutaneous nevi that considered the precursors of low-CSD melanomas." (PMID 35706047, 2022). "Overall, despite the marginal effect on the iORR, the addition of anti-PD-L1 to BRAF/MEK inhibitors in BRAFV600-mutant melanoma seemed to result in higher OS rates." (PMID 36428582, 2022). "Cutaneous melanoma ranks amongst the tumor types with the highest rate of oncogenic mutations in members of the RAS–ERK pathway: 15–20% of melanomas harbor mutant NRAS, whereas oncogenic BRAF appears in 50–60% of the cases." (PMID 36358912, 2022). "In a small retrospective study evaluating 25 patients with BRAF-mutant melanoma, the treatment with immunotherapy after a BRAF inhibitor resulted in higher ORR, compared to giving immunotherapy before a BRAF inhibitor (43.8% vs. 0%)." (PMID 35326677, 2022). "Our results showed that LL‐Z1640‐2 and patulin are promising compounds that decrease ZIC5 expression levels and induce apoptosis in various cancer cells, including melanoma, BRAF‐inhibitor resistant melanoma, pancreatic cancer and cholangiocarcinoma cells." (PMID 36282887, 2022). "Mutations in the BRAF gene are present in 50–60% of melanomas and the CDKN2A gene is altered in 16–41% of melanomas." (PMID 36143291, 2022). "According to our understanding, this melanoma feature impacts survival due to the possibility of having additional treatment options with BRAF/MEK inhibitors." (PMID 36497248, 2022). "In the past 10 years, melanoma treatment has made significant progress, from targeting oncogenic BRAF and MEK to checkpoint blockade immunotherapy." (PMID 36551302, 2022). "Our nation-wide prospective study failed to establish any optimal systemic therapy sequencing patterns in advanced BRAF-mutant melanoma patients." (PMID 35323326, 2022). "To further examine the effect of lj‐2‐66 on the viability of BRAF‐mutant melanoma cells, we conducted a colony formation assay." (PMID 35332658, 2022). "This is an important consideration in targeting BRAF melanoma, and perhaps tumors driven by L597R, as it has been observed that elevated CRAF levels represent a mechanism for acquired resistance to BRAF inhibition." (PMID 35883461, 2022). "In melanoma, there are reports of tumors that initially acquired resistance to BRAF inhibitor, responding to a rechallenge following a period where therapy was discontinued, suggesting that this phenotype can arise in patients." (PMID 36418460, 2022).
melanoma (continued). "Together, these results indicate that fibroblasts assembled and remodeled matrices that provide a drug‐tolerant environment for BRAF mutant melanoma cell lines and short‐term cultures." (PMID 34957688, 2022). "Activation of BRAF, accounting for 41–55%, is the most common genetic alteration in the occurrence of melanoma." (PMID 36181568, 2022). "To this aim, we analyzed the RECI2 cohort, which includes 14 BRAF-mut advanced melanoma patients admitted to dabrafenib+trametinib therapy at the Regina Elena Cancer Institute." (PMID 35440004, 2022). "We also showed that inhibition of MARCKS activity not only reduced the invasion and migration of BRAF inhibitor-resistance melanoma cells, but also their metastatic capacity." (PMID 36551563, 2022). "Tumours responding to BRAF/MEK inhibitors have been shown to have increased T cell infiltration, improved T cell recognition of melanoma associated antigens and reduced production of immunosuppressive cytokines." (PMID 35133615, 2022). "In melanoma, BRAF VAF was identified as a potential prognostic and predictive biomarker for treatment response to BRAF inhibitors." (PMID 36143252, 2022). "Until results from future randomized clinical trials become available, our study provides real-world evidence to potentially better guide clinicians in choosing first-line therapy in BRAF V600E/K-mutant melanoma patients." (PMID 35323326, 2022). "Most BRAFV600-mutant melanoma patients treated with first-line standard of care, BRAF and MEK inhibitors, show impressive initial responses, but almost all experience disease relapse within a year." (PMID 35193687, 2022). "In a small cohort of melanoma patients, where tumours are predominantly driven by mutant BRAF(V600E), USP28 is genetically lost." (PMID 35364627, 2022). "Mechanistically, we show that in BRAF-mut melanoma cells, SEMA6A remodels actin cytoskeleton by activating the RhoA-YAP axis." (PMID 35440004, 2022). "In melanoma samples, NRAS mutations co-occurred much less frequently with BRAF mutations than expected." (PMID 36275468, 2022). "CDKN2A depletion is recurrently acquired by 7%-28% progressed melanoma patients on treatment with BRAFi or BRAF/MEKi 80, 85, which facilitates tumor cells to overcome cell cycle arrest and subsequent apoptosis." (PMID 35966590, 2022). "Recently, Phadke and colleagues tested the sequence IT→TT, which they defined as two doses of anti-PD-1 every five days followed by daily dabrafenib/trametinib treatment in a BRAF-mutant murine melanoma model." (PMID 35806358, 2022). "It has been shown that treatment with MAPKi leads to increased numbers of TAM in melanoma lesions, and that tumor necrosis factor (TNF) released by TAMs induces melanoma resistance to MAPKi, blocking apoptosis mediated by inhibition of BRAF signaling." (PMID 35879777, 2022). "Using the conditional BRAF oncogene-driven murine melanoma model, this work demonstrates that co-treatment of the MEK inhibitor trametinib along with the autophagy inhibitor chloroquine induced an enhanced therapeutic effect." (PMID 35847840, 2022). "More importantly, inhibiting SREBP-1 through pharmacological intervention re-sensitized BRAF-mutant melanoma cells to BRAF inhibitor therapies, demonstrating that combinational SREBP-1 and BRAF inhibitors are more effective in targeting drug-resistant cells." (PMID 35884561, 2022). "In the melanoma cells resistant to BRAF inhibitors, glycolysis inhibition was shown to be able to induce cell death." (PMID 36034839, 2022). "Bioinformatic analyses of melanoma gene expression datasets revealed different subsets of BRAF/NRAS melanomas that differ in the endogenous expression of MITF independently of the oncodriver mutation." (PMID 35580987, 2022). "Vemurafenib, a BRAF-inhibitor, clinically used in melanoma treatment, was applied systemically to BRAFWT (mOS-REpA11), BRAFV600E (mOS-REpSK-MEL-28) and non-melanoma skin equivalents." (PMID 36175453, 2022).
melanoma (continued). "Another ongoing study is exploring the efficacy of BKM120 (buparlisib—PI3K inhibitor) in combination with LGX818/MEK162 (BRAF inhibitor/MEK inhibitor) in treating BRAF V600 melanoma." (PMID 35954441, 2022). "Melanoma has certainly been one of the most studied cancers and the most analyzed skin cancer in zebrafish, since the first description of BRAF V600E model." (PMID 35713744, 2022). "Gene signatures have been proposed to identify genes with differential regulation between BRAF V600E‐mutant and wild‐type patients in melanoma." (PMID 35044091, 2022). "The prognosis of melanoma is much poorer; however, there is a well-established clinical staging system for melanoma as well as crucial target biomarkers such as BRAF." (PMID 36324094, 2022). "BRAF inhibitors (BRAFi) can achieve initial efficacy when used to treat melanoma patients, but drug resistance and relapse are common, emphasizing the need for new therapeutic strategies." (PMID 35141161, 2022). "The most frequently targeted cellular pathway in melanoma is the MAPK/ERK pathway, activated by the RAS and BRAF mutations in most melanoma patients." (PMID 35159386, 2022). "Small molecule BRAF inhibitors such as dabrafenib and vemurafenib are highly effective for initial treatment of BRAF V600E melanomas." (PMID 36358868, 2022). "SEMA6A expression was assessed by immunohistochemistry in melanoma cohort RECI1 (N = 112) and its prognostic potential was investigated in BRAF-mut melanoma patients from DFCI and TCGA datasets (N = 258)." (PMID 35440004, 2022). "Nonetheless, the oncogenic role of miR-1246 has been reported in melanoma by conferring resistance to BRAF inhibitors or enhancing migration and invasion through the adhesion molecule CADM1 in hepatocellular cancer." (PMID 36551682, 2022). "A phase Ib/II study (NCT01543698) evaluated triple combination therapy with encorafenib, binimetinib and ribociclib in patients with BRAF V600 mutant melanoma naive to prior BRAF inhibitor treatment and with high tumor burden." (PMID 35053435, 2022). "Here we demonstrate that inhibition of MAPK using MEKi, and the combination of BRAFi with MEKi in vitro, modulates NKG2D-ligands in BRAF-mutant and WT melanoma cells, together with other NK activating ligands." (PMID 36726591, 2022). "For example, under an acidic environment, BRAFv600E melanoma cells manifested active proliferation, enhanced antiapoptotic ability, and exhibited more resistance to the BRAF inhibitor vemurafenib." (PMID 35069734, 2022). "For example, the BRAF inhibitor encorafenib can be used in combination with the MEK inhibitor binimetinib to treat advanced BRAFV600E/K-mutant melanoma." (PMID 35310910, 2022). "This strengthens a concept of the clinical combination of BRAF inhibition and high-dose ascorbate to tackle melanoma cells with acquired resistance to the BRAF inhibition and to exploit potential additive effects of their combination." (PMID 35406796, 2022). "A German real-world study showed, for advanced melanoma patients with mutant BRAF (V600E/K), a higher overall survival of 29 months for those receiving PD-1 compared with 12 months for those receiving dual MAPKi." (PMID 35681781, 2022). "Recently, a large clinical study analyzed ctDNA isolated from plasma samples obtained at baseline from 556 patients with BRAF V600E/K SNV positive melanoma who were enrolled in BREAK-2, BREAK-3, BREAK-MB, and METRIC studies." (PMID 35205608, 2022). "To the best of our knowledge, we show for the first time that ascorbate has a cytotoxic effect on explicitly BRAF mutant melanoma cells including cells with acquired resistance to the BRAF inhibitor vemurafenib or BRAFi/MEKi double resistant cells." (PMID 35406796, 2022).